BRCA1 (BRCA1 DNA repair associated)
Diseases named in the same sentence as BRCA1 in open-access papers (continued):
Sharing a sentence is not in itself a finding about the gene and the disease.
breast cancer (continued). "To further investigate the role of estrogen in Brca1-deficient mammary tumor progression, we isolated a highly metastatic p18−/−;Brca1MGKO tumor cell line from a mammary tumor (tumor B) that was metastasized to lung." (PMID 29996906, 2018). "First, BRCA-associated breast cancer, notably the BRCA1-mutated forms were shown to display a higher immune infiltrate and a higher tumor mutational burden, both being associated with a higher probability of benefit from immunotherapy." (PMID 30544963, 2018). "Recent studies found that breast-cancer-associated mutations in BRCA1 disrupt interaction between BRCA1 and phosphorylated inactivated ACACA (pACACA)." (PMID 29342092, 2018). "Hereditary mutations in BRCA1/2 genes increase the risk of breast cancer by 60–80% and ovarian cancer by about 20–40% in female carriers." (PMID 30040829, 2018). "Taken together, these data provide a comprehensive picture of the genome-wide transcriptional regulation by BRCA1 and suggest some of the identified target genes as biomarker candidates for BRCA1-associated breast cancer." (PMID 29757984, 2018). "Woman aged 50–75 are invited for biennial screening with additional annual screening programs for patients with a cumulative life time risk of breast cancer of over 20% (40–50 years) and BRCA1/2-mutation carriers (25–75 years)." (PMID 29849944, 2018). "We further characterized the interaction of BRCA1 and cyclin B1 and performed preclinical tests of vinblastine, a cyclin B1-inducing agent, in the treatment of BRCA1-associated mammary tumors using a Brca1-mutant allograft model." (PMID 30327455, 2018). "The objective of this pilot study is to evaluate, for the first time, the contribution of germline mutations in BRCA1/2 to breast cancer among Jordanian patients." (PMID 29409476, 2018). "The response rate in patients treated exclusively with carboplatin and paclitaxel was 61.3% that supported the data emerging from the TNT trial favoring the use of platinum compounds in BRCA1/2-associated breast cancer." (PMID 30544963, 2018). "Germline mutations of the BRCA1 gene account for 5–10% of breast cancers and confer a risk of developing the disease 10- to 20-fold much higher than in non-carriers." (PMID 29584711, 2018). "Significant molecular and structural alterations occur in the normal breast prior to the development of BRCA1 associated breast cancer." (PMID 30323900, 2018). "Regarding PARPi pharmacology, olaparib resistance mediated by the overexpression of transporter protein genes (such as the transmembrane pump PgP or ABCB1) has been described in murine models of breast cancer associated with BRCA1 mutations." (PMID 30347758, 2018). "The phosphatidylinositol-3-kinase (PI3K)/AKT signaling pathway regulates cell proliferation, survival, metabolism, EMT, and stem cell fate, and is aberrantly activated in 77% of breast cancers, including BRCA1-deficient disease." (PMID 29996906, 2018). "BRCA1/2 germline mutations have the highest identifiable life-time risk of developing breast cancer ranging from 56 to 80%." (PMID 30544963, 2018). "Hereditary breast and ovarian cancer syndrome (HBOC) represents 5–10% of all patients with breast cancer and is associated with high-risk pathogenic alleles in BRCA1/2 genes, but only for 25% of cases." (PMID 30262796, 2018). "Such strong acceptance by women is notably common, as famously exemplified by the actions (bilateral mastectomy) of an American actress, Angelina Jolie, in reducing her risks of breast cancer after discovering she had BRCA1 gene mutation." (PMID 30112391, 2018). "This is, for example, the case for tumours with high levels of genomic instability, such as Brca1/Brca2-deficient breast cancer models." (PMID 30111589, 2018).
breast cancer (continued). "In Korea, breast cancer cases with early-onset (age < 40) or other indications suggesting a strong genetic burden are entitled to BRCA1/2 mutation testing covered by Korean National Health Insurance." (PMID 30323354, 2018). "Around 5–10% of total breast cancer occurrences are a result of inherited genetic mutations (e.g., BRCA1/2), which leaves an astounding 90–95% of breast cancers that develop due to the influence of outside mediators." (PMID 29849939, 2018). "In most groups, except the male breast cancer group, the BRCA1/2 mutation frequency was higher in Japanese individuals than that in Americans (non-Ashkenazi Jews)." (PMID 29176636, 2018). "Mutations in breast cancer susceptibility gene type 1 and type 2 (BRCA1 and BRCA2) put women at a higher risk of developing breast and/or ovarian cancer." (PMID 29459887, 2018). "In unaffected BRCA1/2 mutation carriers, two breast cancers, which occurred in patients in their 40s, were detected during the observation period of 17.2 months." (PMID 29176636, 2018). "About 5–10% of breast cancers are linked to inherited gene mutations (BRCA-1 and BRCA-2 mutations are the most common), while about 85% of cases occur in women who have no family history of breast cancer." (PMID 30441769, 2018). "If an individual has a family history of breast cancer or has inherited genetic mutations, such as BRCA1 and BRCA2, she is at a significantly higher risk of developing breast cancer." (PMID 29713580, 2018). "The role of somatic BRCA1/2 gene mutations in breast cancer is getting increasing attention in view of hereditary disease." (PMID 29453630, 2018). "BRCA1-associated breast cancers exhibit the pathological features of an aggressive phenotype, and are usually hormone receptor-negative, whereas BRCA2-assocated breast cancers tend to resemble sporadic cancers, and are predominantly hormone receptor-positive." (PMID 30572612, 2018). "This insight came from studies of women carrying germline BRCA1 or 2 mutations, which make these women more prone to malignancies, particularly ovarian cancer as well as breast cancer." (PMID 30424539, 2018). "Of 127 BRCA1 mutation carriers, 94 had a history of or were currently suffering from breast cancer (67 single cases, 24 cases with 2 simultaneously metachronous breast cancers, 3 with 3 simultaneous or metachronous cancers)." (PMID 29176636, 2018). "The transcriptional link between BRCA1 and DNMT1 strongly indicates a function of BRCA1 in global DNA methylation, thus providing another plausible mechanism for BRCA1 mutation-associated DNA hypomethylation and breast cancer formation." (PMID 30558184, 2018). "The distribution of BRCA1/2 mutations identified differed by breast cancer subtype, with BRCA1 mutations predominated among TNBC (94%, 15/16) while BRCA2 mutations predominated among patients with HR and/or HER2-positive MBC (75%, 12/16)." (PMID 30318518, 2018). "The lifetime risk for breast cancer in a male BRCA1 mutation carrier is just over 1%, and it is estimated that a BRCA1 mutation is present in up to 4% of MBC cases." (PMID 29697934, 2018). "Cisplatin has an effective role in breast cancer, especially BRCA1-associated cancers, which are normally triple-negative type." (PMID 29950928, 2018). "We received data from 84 Chinese breast cancer patients who had known pathogenic BRCA1/2 mutations, which included 63 different types of mutations (22 BRCA1 and 41 BRCA2)." (PMID 29487695, 2018). "Two genetic markers, not often used to describe a type of breast cancer, but rather to estimate an individual's predisposition to developing it, are the breast cancer 1 and breast cancer 2 (BRCA1 and BRCA2) genes." (PMID 29713580, 2018). "According to the most recent meta-analysis, the cumulative breast cancer risk by age 70 years was estimated to be 55% (95% CI: 50-59%) and 47% (95% CI: 42-51%) for Caucasian women carrying a BRCA1 or BRCA2 mutation respectively." (PMID 29861850, 2018).
breast cancer (continued). "In a phase II study, two cohorts of 27 patients with confirmed BRCA1 or BRCA2 mutation-advanced breast cancer were enrolled and treated with two different doses of olaparib." (PMID 30234015, 2018). "The incidence rate of contralateral breast cancer in a BRCA1/2 mutation carrier was 0.99%/year, which was three times higher than that for a person without the mutation." (PMID 29176636, 2018). "The BRCA1 gene is located on chromosome 17q21, and its mutations are associated with a high risk of breast cancer in women with a lifetime risk of 50–85%." (PMID 29757984, 2018). "Mutations in BRCA1 or BRCA2 have been detected in 20% of families with a history of breast cancer in Poland." (PMID 29678143, 2018). "In patients with breast cancer, mutations in the BRCA1/2 genes account for 5% of all breast cancers and 15–20% of all hereditary breast cancers." (PMID 29313279, 2018). "Taken together, germline BRCA1/2 mutations in EOC patients showed a distinct mutational spectrum compared to our previously published data on breast cancer patients." (PMID 30103829, 2018). "Still, larger studies with a longer time since IVF treatment are needed to exclude a small increased breast cancer risk and to investigate the long-term breast cancer risk for BRCA1/2 mutation carriers." (PMID 29937543, 2018). "Three contralateral breast cancers occurred in BRCA1/2 mutation carriers (3/302.6 person-years), and the annual incidence rate was 0.99%." (PMID 29176636, 2018). "Germline BRCA1/2 carriers have high risk of both ovarian and breast cancer (lifetime risk: 10-60% for ovarian cancer; 66–82% for breast cancer)." (PMID 30424539, 2018). "We discovered associations between breast cancer and germline alteration of the Fanconi anemia and tumor suppressor gene set, which are likely driven by BRCA1/2 germline variants." (PMID 30217226, 2018). "Within a biobank research study of somatic mutations in breast carcinomas, ten germline BRCA1/2 mutations were incidentally detected." (PMID 29082482, 2018). "In the prevalence table, Japanese individuals had a higher mutation-positive rate for BRCA1/2 than Americans (except for Ashkenazi Jews) in almost all groups except for the male breast carcinoma groups." (PMID 29176636, 2018). "By comparison, BRCA1 mutation-carrying men have an estimated cumulative risk of 1.2% of developing breast carcinoma at the same age." (PMID 30558184, 2018). "In breast cancer (BC), the efficacy results of the PARPi olaparib (Lynparza®) in metastatic patients carrying a germline BRCA1/2 (gBRCA) pathogenic variant have led to its recent approval by the Food and Drug Administration." (PMID 30377213, 2018). "Since PARP1 inhibition induces accumulation of DNA damage in BRCA1-deficient cells, we tested if inhibition of EZH2 enhances the effect of the PARP inhibitor olaparib in BRCA1-mutated and BRCA1-reconstituted MDA-MB-436 human breast carcinoma cells." (PMID 29535829, 2018). "Women with BRCA1/2 mutations indicated strong preferences for breast cancer risk reduction and maintaining fertility." (PMID 28624978, 2017). "Here, we detected BRCA1/2 mutations in 13.2% of high-risk breast cancer patients who were referred to a genetic counseling center." (PMID 28205045, 2017). "Breast cancer risk increases dramatically in women carrying mutations in a breast cancer susceptibility gene, most frequently BRCA1 or BRCA2." (PMID 28977823, 2017). "Several studies have reported an increased risk for developing breast cancer in women with either BRCA1 or BRCA2 mutations following exposure to medical radiation, either through mammography or radiation therapy." (PMID 28865460, 2017).
breast cancer (continued). "In the setting of breast cancer, a proof of concept study was conducted to assess the efficacy, safety, and tolerability of olaparib alone in women with BRCA1 or BRCA2 mutation advanced breast cancer." (PMID 28454587, 2017). "Breast cancer susceptibility genes 1 and 2 (BRCA1 and BRCA2) mutations are associated with hereditary breast and ovarian cancer syndromes (HBOC)." (PMID 28706762, 2017). "We observed a higher proportion of reports of breast cancer before the age of 50 in families with pathogenic BRCA1 mutations (p = 0.005)." (PMID 27926510, 2017). "Absence of the estrogen receptor-α (ER) is perhaps the most distinctive pathological feature of breast cancers arising in women who inherit a mutation in BRCA1." (PMID 28270739, 2017). "Mutations in BRCA1 are associated with predisposition to ER− breast tumors, whereas most known common susceptibility loci for breast cancer show stronger associations with ER+ than with ER− tumors." (PMID 28761624, 2017). "Of the evaluated breast cancer cell lines with mutations in BRCA1 (MDA-MB-436 and HCC-1937) or BRCA2 (HCC-1569, BT-20, BT-474, MDA-MB-361), only one (HCC-1569) was found to respond to BMN-673." (PMID 28649435, 2017). "This observed link between BRCA1 expression and basal-like breast cancer in our study is supported by similar findings from previous studies showing that the majority of BRCA1-associated tumors express basal cytokeratins." (PMID 28863181, 2017). "More than 25 breast cancer susceptibility genes have been identified so far, most of which play a role in the DNA repair pathway linked to BRCA1 and BRCA2." (PMID 28339459, 2017). "KB1P mice develop mammary tumors that mimic the histopathological features of human BRCA1‐mutated breast cancers as well as their hypersensitivity to platinum drugs and PARP inhibitors." (PMID 28028012, 2017). "TNBCs account for 15-20% of all breast cancers and are associated with an earlier onset, BRCA1 mutations and patients of African descent." (PMID 29113326, 2017). "This study analyzed VDR, RXR and PPARγ by immunohistochemistry in BRCA1 associated (n = 38) and sporadic breast cancer (n = 79)." (PMID 28427429, 2017). "The HR of breast cancer was 5.90 (95% CI 2.01 to 17.33) for BRCA1 and HR = 2.55 (95% CI 0.49 to 13.13) for BRCA2 mutation carriers compared to non-carriers." (PMID 28680148, 2017). "Linkage analysis followed by positional cloning has been successfully applied to identify the high penetrance breast cancer susceptibility genes BRCA1 and BRCA2." (PMID 29262523, 2017). "In conclusion, our comprehensive evaluation of BRCA1/BRCA2 in families with criteria for hereditary breast cancer found three known BRCA1/BRCA2 mutations and BRCA1 c.4647_4648dupAA as a novel pathogenic." (PMID 28944232, 2017). "BRCA1 promoter methylation analysis has been proposed as a cost-effective and reliable prescreening tool to exclude BRCA1 germline mutations in patients with breast cancer similar to MLH1 promoter methylation and Lynch syndrome." (PMID 28569220, 2017). "In summary, Nestin was strongly associated with germline BRCA1 related breast cancer, a basal-like phenotype, reduced survival, and stemness characteristics." (PMID 28439082, 2017). "When personal factors were considered, BRCA1/2 mutations were observed in 11.6% of early-onset breast cancer patients, 14.9% of bilateral breast cancer patients, and 66.7% of patients who were diagnosed with both breast and ovarian cancer." (PMID 28205045, 2017). "The TN phenotype is the most common histological subtype observed in patients with BRCA1/2 mutations or ‘BRCAness’ breast cancer." (PMID 29152070, 2017). "TNBC is an important factor used to select breast cancer patients for BRCA1/2 mutation testing and this was confirmed in our study." (PMID 28205045, 2017).
breast cancer (continued). "This case report describes a BRCA1 germline mutation identified in a woman with stage IV epithelial ovarian cancer and the provision of genetic counseling about BRCA1-associated breast cancer risk in the three years following diagnosis." (PMID 28780755, 2017). "Data in several previous reports also demonstrated that patients with OC and pathogenic germline BRCA1/2 variants frequently lack a family history of breast cancer/OC." (PMID 29348823, 2017). "Several papers have already described the association of BRCA1 promoter hypermethylation with sporadic breast cancer." (PMID 28403857, 2017). "Our studies show that Pol II pausing is an important contributor to BRCA1-associated R-loop accumulation and breast cancer development." (PMID 28649985, 2017). "Because of the relative rarity of BRCA1 mutation in the general breast cancer population, however, these studies are often underpowered, making clinical impact for mutation carriers limited." (PMID 28851423, 2017). "In the single-variant association testing using logistic regression, BRCA1 p.Arg762Ser was associated with breast cancer risk with a marginal significance (OR = 7.4; 95% CI, 0.9–62.3; p = 0.06)." (PMID 28222693, 2017). "We recently highlighted thyroid hormone receptors (TRs) to predict prognosis in breast cancer patients that had been diagnosed a BRCA1 germline mutation." (PMID 28427429, 2017). "In the familial non-BRCA1/2 mutated breast cancer patients with strong family history, glycodelin is more frequently expressed in the tissues with malignant features including lymph node metastasis, positive HER2, and negative ER, and PR status." (PMID 29238349, 2017). "Examples for hypermethylated breast cancer-associated genes are BRCA1, CCND2 (cyclin D2), ER, PR, CDH1 (E-cadherin), and many others." (PMID 29138528, 2017). "Evidence of association with breast cancer risk (at p < 10−2) was observed for nine SNPs in BRCA1 mutation carriers and three SNPs in BRCA2 mutation carriers." (PMID 27796716, 2017). "In conclusion, Nestin was associated with germline BRCA1 related breast cancer, a basal-like phenotype, as well as high-grade tumour features and reduced survival by multivariate analysis." (PMID 28439082, 2017). "Germline mutations in the BRCA2 gene are a risk factor for both male and female breast cancer, but mutations in the BRCA1 gene appears to be a risk much more for female breast cancer than for male breast cancer." (PMID 27286002, 2017). "BRCA1 is involved in regulating cell cycle control and DNA repair and is known to pose a hereditary risk for breast cancer." (PMID 29017547, 2017). "Genetic complementation between mouse Brca1 and Cobra1 in R-loop dynamics and mammary tumorigenesis strongly suggests that COBRA1 contributes to BRCA1-associated breast cancer development." (PMID 28649985, 2017). "Usually, the recommended treatment for hereditary breast cancer associated with BRCA1 mutation is mastectomy because it is a more aggressive cancer with a poor prognosis." (PMID 28741261, 2017). "Sporadic breast cancers account for approximately 90–95% of breast cancers, while familiar breast cancers account for the remaining 5–10% due to mutations in genes such as BRCA1/2 in breast cancer families." (PMID 28301567, 2017). "In the largest follow-up study of BRCA-mutated patients in the Hereditary Breast Cancer Study Group, eight new cases of pancreatic cancer were identified, out of 5089 women, in the database of BRCA1 and BRCA2 carriers, versus 3.28 expected pancreatic cancers." (PMID 29069866, 2017). "Considering the importance of estrogen-based signaling in the genesis and progression of breast cancer, this characteristic of BRCA1-linked breast cancers has important consequences for the treatment and prevention of these cancers." (PMID 28270739, 2017).